IL1B (interleukin 1 beta)
Diseases named in the same sentence as IL1B in open-access papers (continued):
Sharing a sentence is not in itself a finding about the gene and the disease.
dermatitis (continued). "The pathogenic T cells which secrete cytokines can activate the NLRP3 inflammasome of keratinocyte, then caspase-1 mediated pro IL-1β cleavage will produce active IL-1β exacerbating skin inflammation." (PMID 37686332, 2023). "In KCASP1Tg mice, various inflammatory cytokines, including IL-1β, are released from dermatitis skin lesions into the blood." (PMID 36983014, 2023). "More importantly, the expression of IL1B induced hyper-activation of IL-1R1-expressing mast cells, while the treatment of anti-IL1B antibody can reduce the aggravation of dermatitis in spontaneous mice models of AD with a defective skin barrier." (PMID 37330465, 2023). "The study was also able to reveal that treatment with anti-IL-1β-antibody alleviated the exacerbation of dermatitis." (PMID 37511138, 2023). "Numerous studies have reported that IL-1β contributes to skin inflammation in AD and induces IL-6 production both in vitro and in vivo." (PMID 37175425, 2023). "Compared with wild-type mice, Rev-erbα-/- mice showed an increased sensitivity to P. acnes-induced skin inflammation, as evidenced by higher levels of pro-inflammatory factors such as Cxcl1, Il-1α, Il-1β, Il-6 and Tnf-α in the knockout mice." (PMID 35414779, 2022). "Compared with normal mice, jet-lagged mice were more sensitive to P. acnes-induced skin inflammation, as evidenced by higher levels of pro-inflammatory factors such as Cxcl1, Il-1α, Il-1β, Il-6 and Tnf-α." (PMID 35414779, 2022). "Of note, previous studies have demonstrated that IL1β is an essential cytokine for synergistically acting with IL-23 to stimulate IL-1R1+ γδ T cells to producing IL17 in skin inflammation." (PMID 35922852, 2022). "Other studies highlighted the anti-inflammatory role of Nrf2 signaling in reducing the levels of IL-1β and IL-6 to alleviate skin inflammation besides suppressing the activation of inflammatory NF-κB and NLRP3 pathways." (PMID 33424605, 2020). "Filaggrin mutation in mice results in spontaneous skin inflammation and increases in the ILC2 population, IL-1β production, and other cytokines related to AD in skin." (PMID 32326002, 2020). "We crossed Il1a−/−, Il1b−/−, and Il1r1−/− mice onto the Flgft/ft background to investigate their contribution to spontaneous skin inflammation." (PMID 30937919, 2019). "Instead, the development of skin inflammation was dependent on an interplay between microbiota, IL‐1β, and mast cells." (PMID 30937919, 2019). "In summary, we revealed a critical role of IL‐1β in the initiation and maintenance of skin inflammation in a mutant mouse model of defective skin barrier." (PMID 30937919, 2019). "Treatment with anti‐IL‐1β‐antibody alleviated dermatitis exacerbation, while antibiotic intervention ameliorated dermatitis in neonatal mice but not in adults with established inflammation." (PMID 30937919, 2019). "We found that the most relevant cytokines for the oxazolone model were IL-1β, TNFα, IL-4, and IL-6, which shared more than 25% of their variation with the variation in ear thickness in all dermatitis induced mice." (PMID 28290517, 2017). "According to the literature, the IL-1β facilitates specific inflammatory mechanism of IL-22 in the skin disorders." (PMID 29312598, 2017). "Altogether, our study further highlights a specific role of IL-1β in provoking dermatitis in Sharpincpdm mice and provides additional evidence advocating the use of specific IL-1 targeted therapies in the treatment of inflammatory diseases." (PMID 27892465, 2016). "We also showed that aggravated dermatitis and pruritus in the AD rats were related to the elevated expression of Th1 cytokines, such as TNF-α and IL-1β, which are known to be associated with chronic AD lesions." (PMID 28005965, 2016). "ID significantly reduced DNFB-induced dermatitis and decreased the serum levels of IgE and the IL-1β via the inhibition of p38, ERK, and JNK phosphorylation as well as the activation of NF-κB in AD-like skin lesions." (PMID 26104582, 2015).
dermatitis (continued). "Consistent with these previous findings, our results demonstrate that NGO injection reduces IL1β production by DCs during OVA-induced AD-like skin inflammation, prompting us to speculate that DCs might be one of the target cells of NGO action." (PMID 39199350, 2024). "It is hypothesized that propionate and HFD may not induce the generation of Foxp3+ Tregs in imiquimod-induced dermatitis, which might contain a large amount of IL-6, IL-1β, or IL-23 counteracting their generation." (PMID 37762500, 2023). "Initiation of skin inflammation by P. acnes involves activation of inflammatory cells, monocytes, keratinocytes and sebocytes and subsequent secretion of inflammatory cytokines and chemokines such as IL-1α, IL-1β, IL-6, IL-8 and TNF-α 43-45." (PMID 35414779, 2022). "Concerning the mode of action of icIL-1Ra1 in the skin, extracellular icIL-1Ra1 released by keratinocytes has been proposed to counter-regulate skin inflammation provoked by keratinocyte-derived IL-1α and/or by IL-1β, the latter mainly produced by infiltrating myeloid cells." (PMID 33796114, 2021). "Daily intraperitoneal injections of ΔKerOTULIN mice with Anakinra starting from P18 onwards could suppress dermatitis development in the back skin and tail of these mice, confirming an important contribution of IL-1β in the development of skin lesions." (PMID 34625556, 2021). "Consequently, pharmacological inhibition of IL1β signaling suppressed dermatitis development in ΔKerOTULIN mice." (PMID 34625556, 2021). "IL-1β and IL-1R1 signaling plays a critical role in chronic dermatitis inflammation in Filaggrin-mutant mice because anti-IL-1β antibody treatment alleviated dermatitis symptoms." (PMID 32326002, 2020). "AD-like dermatitis induced through FLG-deficiency was dependent on IL-1β and IL-1R1 signaling, but not NLRP3 inflammasome activation." (PMID 32528469, 2020). "Indeed, IL-1β and IL-18 play key roles in skin disorders, and several therapeutic drugs have been developed to target inflammasome activation as well as IL-1β signaling." (PMID 32933004, 2020). "Imiquimod-induced skin inflammation is partially reduced in mice deficient for both IL-1α/IL-1β or for IL-1R1, but not in IL-1α- or IL-1β-deficient mice, demonstrating the redundant activity of IL-1α and IL-1β for skin inflammation." (PMID 31156649, 2019). "We studied the synergistic effects of RR on keratinocytes and demonstrated that RR potently suppressed skin inflammation by inhibiting expression of pro-inflammatory cytokines, such as IL-6 and IL-1β in TNF-α/INF-γ-induced human keratinocytes and 3D human skin tissue model." (PMID 30901835, 2019). "The HIGH and the LOW phenotypes from the conventional mice were clearly transferred to germ-free mice, as there was a higher expression of dermatitis score, ear thickness, IL-1β, TNFα, IL-4, and IL-6 in the HIGH mice compared to the LOW mice, and for most of these also higher than the CONV mice." (PMID 28290517, 2017). "Collectively, our study indicates that bathing with HMW ameliorates DNCB-induced skin inflammation by inhibiting the allergic response (such as serum IgE level and scratching behavior), inflammatory response (such as inflammatory cytokines; IL-1β, TNF-α, and IL-13) in female skh-1 hairless mice." (PMID 29029618, 2017). "However, Sharpincpdm × Il1b−⁄− mice eventually developed dermatitis, as shown for 70-day-old Sharpincpdm × Il1b−⁄− mice." (PMID 27892465, 2016). "Our data herein demonstrate a specific role for IL-1β in promoting dermatitis in Sharpincpdm mice." (PMID 27892465, 2016). "Both IL-1α and IL-1β were dramatically increased in KIL-18Tg(+) mice after onset of dermatitis." (PMID 25119884, 2014). "Increased IL1β production during skin inflammation reduces the expression of filaggrin, a protein essential for skin barrier function, which suggests that the down-regulation of filaggrin might be related to increased transepidermal water loss and increased permeability to allergens." (PMID 39199350, 2024).
dermatitis (continued). "COX-2, IL-1β, and VEGF play crucial roles in skin inflammation and erythema through interlinked mechanisms." (PMID 40864771, 2025). "CA-infected mice showed extensive dermatitis, confirmed by strong iNOS, TNF-α, IL-1β, and NF-κB genes or immune expressions." (PMID 38858704, 2024). "In the context of skin inflammation, inflammatory cytokines such as TNF-α, IL-17A, and IL-22 induce keratinocytes to produce proinflammatory cytokines, including IL-1β, IL-6, TNF-α, and IL-23, which subsequently influence the liver to increase SAA production." (PMID 39519167, 2024). "Our study demonstrated that HPs effectively modulated the production of IL-1β, IL-6, and TNF-α, resulting in a significant reduction in UV-induced skin inflammation." (PMID 38539828, 2024). "Oral propionate and the HFD reduced mRNA expression of IL-17A, IL-17C, IL-17F, IL-22, IL-1β, IL-6, TNF-α, CXCL1, CXCL2, and CCL20 in imiquimod-induced dermatitis." (PMID 37762500, 2023). "Oral propionate decreased mRNA expression of IL-17A, IL-17C, IL-17F, IL-22, IL-6, IL-1β, TNF-α, CXCL1, and CCL20 in imiquimod-induced dermatitis in comparison between NDIS versus NDIP." (PMID 37762500, 2023). "The HFD decreased mRNA expression of IL-17A, IL-17F, IL-22, TNF-α, IL-1β, CXCL1, CXCL2, and keratin 16, and increased mRNA expression of TGF-β1 and CDKN1A in imiquimod-induced dermatitis." (PMID 37762500, 2023). "Oral propionate reduced inflammatory infiltrates and epidermal Ki67+ cells and reduced mRNA levels of IL-17A, IL-17F, IL-17C, IL-22, IL-1β, IL-6, TNF-α, CXCL1, CCL20 and increased those of TGF-β1and IL-10 in imiquimod-indued dermatitis." (PMID 37762500, 2023). "Mangiferin, obtained from Mangifera indica, can ameliorate the skin lesions prominent in dermatitis by reducing the inflammatory biomarkers such as IL-6, TNF-α, and IL-1β." (PMID 35626720, 2022). "Proinflammatory cytokines and chemokines secreted by keratinocytes, such as TNF-α, IFN-γ, IL-1β, IL-6, IL-8, TARC (CCL17), MDC (CCL22), and RANTES, play a very important role in dermatitis." (PMID 34361003, 2021). "Kopfnagel found that human keratinocytes express AIM2 and respond to dsDNA with IL-1β secretion, indicating that the AIM2 inflammasome is a trigger for skin inflammation." (PMID 32528469, 2020). "OIR3 was able to reduce oxazolone-induced skin inflammation in allergic dermatitis mouse model via the inhibition of TNF-α, IL-1β and IL-6 mRNA expression." (PMID 31775224, 2019). "Filaggrin‐mutant (Flgft/ft) mice develop spontaneous skin inflammation accompanied by an increase in skin ILC2 numbers, IL‐1β production, and other cytokines recapitulating human AD." (PMID 30937919, 2019). "Further evaluation of its anti-inflammatory abilities in vivo revealed that OIR3 exhibited therapeutic effects by inhibiting oxazolone-induced skin inflammation via inhibition of TNF-α, IL-1β and IL-6 mRNA expression." (PMID 31775224, 2019). "In TPA-induced skin inflammation, TNF-α and IL-1β in the serum were reduced by 70% ethanol extract from Asparagus cochinchinensis." (PMID 28358324, 2017). "IL-1β and TNF are important in this model, since both Il1r1−/− and Tnf−/− mice showed significantly reduced dermatitis." (PMID 27982014, 2016). "Aryl hydrocarbon receptor (AhR) activation suppresses autophagy and promotes skin inflammation through the NF-Kappa B (NF-κB)/p38 mitogen-activated protein kinase (MAPK) signaling pathway, leading to inflammatory cytokine secretion (IL-1β, IL-6, and TNF-α) in keratinocytes." (PMID 40332377, 2025). "When the Sharpincpdm mice were crossed with mice deficient in the IL-1 receptor (Il1r−/−), which mediates signals from both IL-1α and IL-1β, the absence of IL-1R delayed the progression of dermatitis in the Sharpincpdm mice." (PMID 40006996, 2025). "IL-1β and CXCL2 have been demonstrated to play pivotal roles in the pathogenesis of dermatitis." (PMID 41296413, 2025).
dermatitis (continued). "Further investigation on Sharpincpdm Il1a−/− mice and Sharpincpdm Il1b−/− revealed that IL-1β, but not IL-1α, delayed the onset of dermatitis at the median age of 60 days as compared to Sharpincpdm mice at the median age of 42.5 days." (PMID 40006996, 2025). "The expression levels of IL-1β, IL-4, IL-6, and TNF-α in peripheral blood positively correlate with the severity of dermatitis and may contribute to disease recurrence." (PMID 39748922, 2024). "HFD reduced mRNA levels of IL-17A, IL-17F, IL-22, IL-1β, tumor necrosis factor (TNF)-α, CXCL1, CXCL2, and keratin 16 and increased those of transforming growth factor (TGF)-β1 and cyclin-dependent kinase inhibitor 1A in imiquimod-induced dermatitis." (PMID 37762500, 2023). "In our study, the increased infiltration of macrophages into skin lesions and enhancement of IL-1β and NLRP3 expression suggested that inflammasome activation might be involved in exacerbating skin inflammation." (PMID 37964882, 2023). "The protective effects of PF and PW on UVB-induced skin inflammation and skin barrier damage in human immortalised epidermal keratinocytes (HaCaT) cells (including cell viability, ROS, HO-1, NQO1, IL-1β, IL-8, TNF-α, KLK-7, FLG, AQP3 and Caspase 14 levels) are investigated." (PMID 36771204, 2023). "Keratinocytes lacking OTULIN display a type-1 interferon and IL-1β response signature, and genetic or pharmacologic inhibition of these cytokines partially inhibits skin inflammation." (PMID 34625556, 2021). "Taken together, these results indicate that JNK1 expression in the myeloid compartment contributes to Aldara®-induced skin inflammation through the IL-1β production system rather than by acting downstream of the TLR7 pathway." (PMID 33613525, 2020). "In the present study, we have shown that the development of skin inflammation in Flgft/ft mice is independent of group 2 innate lymphoid cells but requires an interplay between the microbiome, IL‐1β, and mast cells." (PMID 30937919, 2019). "Our results herein demonstrate that IL-1β is specifically required for the development of dermatitis, but not cellular dysregulation, in Sharpincpdm mice." (PMID 27892465, 2016). "Our results further show that the onset of dermatitis is specifically modulated by IL-1β, but not by IL-1α." (PMID 27892465, 2016). "Thus, the NGO-mediated reduction in DC-derived IL1β production may contribute to modulating Th2 cell induction, ultimately attenuating Th2-related, OVA-induced skin inflammation." (PMID 39199350, 2024). "All mice with oxazolone-induced dermatitis had a dramatic increase in IL-1β, IL-4, IL-6, IL-10, TNF-α, IFN-γ, IL-16, IL-17C, IL-17E, IL-17F, IL-21, IL-22, and MIP-3a, whereas the concentrations of IL-12p70, IL-2, IL-17A, and IL-23 were lower in dermatitis mice." (PMID 37889696, 2023). "They produce inflammatory cytokines such as interleukin (IL)-1β, IL-6, IL-8, IL-18, and IL-25 and chemokines such as thymus and activation-regulated chemokine (TARC), cutaneous T cell attracting chemokine (CTACK), and monocyte derived chemokine (MDC) in skin inflammation." (PMID 35626720, 2022). "Hence, we inferred that IL-1ra, as a natural IL-1 receptor antagonist, which downregulate the activity of IL-1β, may be a crucial factor in mediating AEC-SC function on IMQ-induced skin inflammation." (PMID 35922852, 2022). "Furthermore, we demonstrate a specific role for IL-1β, but not IL-1α, in instigating dermatitis in Sharpincpdm mice." (PMID 27892465, 2016). "To elucidate whether the aggravation of dermatitis and pruritus induced by FA exposure is related to the changes in skin Th1 cytokines, we examined whether exposure to 1.2 ppm of FA increased the expression of skin TNF-α and IL-1β in AD and naive rats." (PMID 28005965, 2016). "However, whether IL-1α or IL-1β, both of which signals through IL-1R, instigates skin inflammation and systemic disease is not known." (PMID 27892465, 2016).
co-infection (80 papers, 2012 to 2026). "In our study, Welch’s test was used to determine the significance of differences in the range of the analyzed proinflammatory cytokines, TNF-α, IL-1β and IL-6, associated with the three tested atypical pathogens and their co-infections." (PMID 40647668, 2025). "To investigate the innate immune response caused by IBDV and FAdV co-infection, we examined the mRNA expression levels of IL-6, IL-1β, IFN-α, and IFN-γ in the spleen because it is the principal organ of systemic immunity." (PMID 33926543, 2021). "In co-infection, IL-1β production correlated with decreased weight loss suggesting a protective role." (PMID 24324838, 2013). "We did show that the ability to generate an IL-1β response during co-infection negatively correlated with weight loss, suggesting that IL-1β is protective in this model." (PMID 24324838, 2013). "In addition, compared with PbANKA-mono-infection, co-infection resulted in elevated Gal-1, Gal-3, M1 markers (IL-1β and iNOS), and IL-6 in the peritoneal macrophages, which may be associated with enhanced liver immunopathology during the co-infection." (PMID 32883347, 2020). "The findings indicate that P. gingivalis/F. nucleatum co-infection was characterized by increased alveolar bone loss and TNF-α and IL-1β levels compared to infection by individual agents." (PMID 41228271, 2025). "MHV co‐infection in ZBP1‐deficient mice synergistically amplified Il6 and Tnf expression, whereas Il1b, Cxcl1, and Cxcl5 levels remained refractory to further elevation." (PMID 40810650, 2025). "On the contrary, the IL-1β production in both groups with HIV/TB co-infection was reduced, especially in the HIV/TB group with TB recurrence." (PMID 38790916, 2024). "In a mouse model, co-infection with P. gingivalis and F. nucleatum led to higher releases of IL-1β and TNF-α, as well as an increase in alveolar bone resorption." (PMID 38612423, 2024). "The inflammatory cytokine IL-1β was significantly increased in Em infected mice in the context of both single and co-infection; however, the co-infected mice exhibited a more marked increase as compared to vehicle controls." (PMID 39229265, 2024). "During the acute illness, children with RV‐HBoV1 coinfection were characterized by lower expressions of IL‐1b, MIP‐1b, RANTES, TNFa, TARC, and ENA‐78." (PMID 38006383, 2023). "Among the plasma levels of inflammatory cytokines, the levels of IL-1β were the least specific/selective for HIV-1/TB coinfection." (PMID 37376629, 2023). "Production of IL-1β during influenza/pneumococcus co-infection prevents AMs apoptosis, a process that is protective against S. pneumoniae serotype 14, but not 19, outgrowth." (PMID 36829255, 2023). "The GAS-inducible upregulation of inflammatory genes, such as Nos2, as well as the secretion of TNFα and IL-1β were notably reduced or even abrogated following co-infection." (PMID 36365071, 2022). "In the present study, significant upregulation of IL-1β, transferrin, and C3 gene expression was observed post-turmeric oil treatment in P. hypophthalmus with co-infection conditions." (PMID 36119096, 2022). "The increased production of IL-1β promoted by L. rhamnosus Lr32 in cells challenged with A. actinomycetemcomitans is similar to what was observed in the co-infection of the same probiotic with P. gingivalis on GECs." (PMID 35602018, 2022). "GECs mono-infected with A. actinomycetemcomitans produced CXCL-8, GM-CSF, and IL-1β, and the co-infection with both probiotic strains altered this profile." (PMID 35602018, 2022). "A. actinomycetemcomitans promoted a slight release of IL-1β after 24 h of interaction, which was attenuated by the co-infection with L. acidophilus La5, but increased with L. rhamnosus Lr32 (p < 0.05)." (PMID 35602018, 2022). "The IL-1β mRNA expression in the IBDV-FAdV co-infection group was significantly lower than those in the FAdV at 1 dpi with FAdV-4-HB1501 (p < 0.05)." (PMID 33926543, 2021).